CXCR4 (C-X-C motif chemokine receptor 4)
Diseases named in the same sentence as CXCR4 in open-access papers (continued):
Sharing a sentence is not in itself a finding about the gene and the disease.
prostate carcinoma (continued). "Interestingly, most of these HER2-overexpressing cell lines express CXCR4, which is reportedly associated with haematogenous metastasis in breast, colon and prostate cancer patients, and is known to be regulated by HER2 through the PI3K/Akt pathway." (PMID 17088902, 2006). "For instance, downregulation of CXCR7 protein has been shown to increase migration in some settings, supporting a role for CXCR7 as a decoy receptor that sequesters CXCL12 and thereby counteracts CXCL12/CXCR4-mediated migration in prostate cancer." (PMID 41347146, 2025). "CXCL12 is a chemokine secreted by stromal and pro-inflammatory macrophages in prostate cancer that binds CXCR4 on lymphocytes, tumor cells, and myeloid populations to guide their migration." (PMID 41228234, 2025). "In prostate cancer, docetaxel-treated cells secrete CSF-1 to recruit TAMs, which then activate CXCR4 signaling via CXCL12 secretion, promoting tumor cell survival and resistance to chemotherapy." (PMID 40433363, 2025). "Through the SDF‐1/CXCR4 axis, CAFs contributed to the recruitment and differentiation of monocytes in an immunosuppressive phenotype in a prostate cancer model." (PMID 40179101, 2025). "Inhibition of CXCL12/CXCR4 pathway has been shown to reduce the incidence of bone metastasis in prostate cancer." (PMID 41347146, 2025). "Based on the results of the in vitro and in vivo experiments, CXCR4 promoted prostate cancer stem-like properties by activating β-catenin and its downstream pathways." (PMID 40735647, 2025). "CXCR4 is overexpressed in prostate cancer cells, and its expression correlates with later stage tumours as well as metastasis to both the bones and lymph nodes, a poor prognosis predictor for patients." (PMID 39982274, 2025). "Therapeutic blockade of the CXCL12/CXCR4 axis with CXCR4 inhibitors in prostate cancer models reduces Treg infiltration, restores CD8+; cytotoxicity, and suppresses tumor growth, with the strongest effects seen when combined with IL-2 supplementation." (PMID 41228234, 2025). "Advanced prostate cancers have increased expression of GPCRs such as CXC Motif Chemokine Receptor 4 (CXCR4), lysophosphatidic acid receptor (LPAR), and protease activated receptor 1 (PAR-1)." (PMID 39000269, 2024). "A decrease in the migratory and invasive potential of these androgen-independent prostate cancer cells was achieved also using the flavanonol dihydromyricetin or ampelopsin via downregulation of the CXCR4 protein expression." (PMID 39465008, 2024). "AMD3100 enhanced the sensitivity of prostate cancer to docetaxel treatment in a preclinical model of prostate cancer bone metastases, demonstrating the therapeutic promise of targeting CXCR4." (PMID 39092186, 2024). "This is confirmed by a meta-analysis showing that increased CXCR4 expression in prostate cancer samples correlates to metastases." (PMID 38727318, 2024). "The flavone apigenin was recently shown to downregulate the expression of CXCR4 in a wide variety of human malignant cell lines, including those derived from colon and prostate cancers." (PMID 39465008, 2024). "In the immune microenvironment of bone metastasis from prostate cancer, Tregs can translocate to the bone marrow through C-X-C chemokine receptor 4 (CXCR4)/C-X-C Motif Chemokine 12 (CXCL12)." (PMID 38464516, 2024). "CXCR4 overexpression has also been reported in prostate cancer; studies have shown that CXCR4 is a key regulator of tumor dissemination." (PMID 37190273, 2023). "We examined the expression of SDF1α and its cognate receptor CXCR4 in human prostate cancer (PCa) lesions and the impact of CXCR4 inhibition alone and in combination with single-dose irradiation in orthotopic PCa models in mice." (PMID 36831366, 2023). "Overexpression of PGK1 in prostate cancer cells has been reported to increase cell metastasis through the CXCR4/CXCL12 axis." (PMID 36860848, 2023).
prostate carcinoma (continued). "CXCR4 is an important signaling molecule in cancer metastasis and its downregulation with this treatment suggests UA has potential as a treatment against prostate cancer cell metastasis." (PMID 37108576, 2023). "Apart from that, overexpression of the CXCR4 gene was documented in aggressive phenotypes of prostate tumor tissues, and prostate cancer patients with this phenotypic characteristic often have poor survival rates." (PMID 36826044, 2023). "Osteoblasts in bone marrow express CXCL12, promoting prostate cancer cell invasion of the niche by chemokine signaling by CXCR4 on the invading cells." (PMID 38239314, 2023). "CXCL12/CXCR4 signaling in prostate cancer cells has been shown to express several members of soluble and membrane-type metalloproteinases, MMP-1, MMP-2, MMP-3, MMP-9, MMP-10, MMP-11, and MMP-14 whose expression contribute to cellular migration and invasion." (PMID 38239314, 2023). "The chemokine receptor, CXCR4 signaling regulates cell growth, invasion, and metastasis to the bone-marrow niche in prostate cancer (PCa)." (PMID 36865146, 2023). "CXCR4 is highly expressed in several malignant tumors, including prostate cancer, that confers a more aggressive behavior of cancer cells." (PMID 36863017, 2023). "New targets for prostate cancer are currently being studied, such as neurotensin receptor-1 (NTS1), somatostatin receptor-2 (SST2) or chemokine receptor-4 (CXCR4) —suggested to be expressed in prostate cancer in a few small pilot studies." (PMID 37190273, 2023). "Altogether we have characterized the chemokine signaling axis through CXCR4-PI4KIIIα interaction contributing to the growth of prostate cancer bone metastasis." (PMID 36865146, 2023). "The data support this concept that in prostate cancer cells, endogenous interaction is present between CXCR4 and PI4KIIIα adaptor protein TTC7B." (PMID 37996444, 2023). "SILAC-based quantitative proteomic analysis of lipid raft microdomains identified phosphatidylinositol 4-kinase III-alpha (PI4KA) as a novel downstream modulator of CXCL12/CXCR4 signaling in prostate cancer cells." (PMID 38239314, 2023). "Lipid kinase PI4KA identified as a novel target downstream of CXCR4 in prostate cancer cells and in PC cells chemokine signaling induces PI4KA activation for PI4P production at PM." (PMID 38239314, 2023). "Meanwhile, research also demonstrates that epigenetic modification of the CXCR4 promoter plays a crucial role in the development of bone metastasis in prostate cancer and tumor microenvironment-related chemotaxis." (PMID 37190171, 2023). "CXCR4 overexpression enhanced the PI4P levels in the invasive projections in prostate cancer cells and abrogation of production through knockdown of PI4KIIIα leads to inhibition of chemokine induced PC cell invasion." (PMID 37996444, 2023). "The CXCL12/CXCR4 axis has previously been shown to be involved in prostate cancer cell homing to bone tissue, and new investigations found a novel interaction of Phosphatidyl Inositol 4 kinase IIIa (PI4KA) downstream of chemokine signaling." (PMID 38239314, 2023). "For example, CXCL12, or the stromal-derived factor 1 (SDF-1), is a CXC chemokine, and its receptor CXCR4 is reported to play a critical role in the spread of prostate cancer cells to the bone." (PMID 36826044, 2023). "CXCL12 secreted by stroma cells plays a pivotal role in bone metastasis, and blocking the CXCL12/CXCR4 axis significantly inhibited the BoM process in prostate cancer." (PMID 38187400, 2023). "In this work, we have compared GRP-R, PSMA, NTS1, NTS2, SST2 and CXCR4 expression in vitro in primary prostate cancer samples." (PMID 37190273, 2023). "C-X-C chemokine receptor type 4 (CXCR4) is a receptor that is highly expressed in prostate cancer cells." (PMID 36836717, 2023). "An in vitro study comparing adjacent normal endothelial cells to prostate tumor vasculature highlighted CXCR4 as a potential novel target to interfere with prostate cancer angiogenesis." (PMID 37190273, 2023).
prostate carcinoma (continued). "The involvement of the CXCR12/CXCR4 axis in prostate cancer (PC) bone metastasis has been a promising research focus." (PMID 38239314, 2023). "Transgenic adenocarcinoma of mouse prostate (TRAMP) mice treated with UA showed suppressed CXCR4 expression in the prostate and inhibited metastasis of prostate cancer to distal organs including the liver and lungs." (PMID 37108576, 2023). "CXCL12 (SDF-1)/CXCR4 interactions play an essential role in prostate cancer migration and invasion to the bone by activating Akt1 and MMP-9 expressions." (PMID 36863017, 2023). "Sun and co-workers have reported that in an in vivo study, the extent of bone metastasis in prostate cancer was limited by using a neutralizing antibody against CXCR4." (PMID 36826044, 2023). "Similar to PI4KIIIα knockdown, TTC7B knockdown also significantly inhibited cellular invasion of prostate cancer cells suggesting that TTC7B adaptor mediated recruitment of PI4KIIIα to CXCR4 is critical for chemokine induced PC cell invasion." (PMID 37996444, 2023). "Curcumin inhibits cancer-associated fibroblast-driven prostate cancer invasion, EMT, ROS production, and decreased CXCR4 and IL-6 receptor expression through MAOA/mTOR/HIF-1α signaling." (PMID 38008819, 2023). "DHM effectively suppresses the proliferation of prostate cancer cells by reducing angiogenesis and prevents in vitro migration and invasion of PC-3 human prostate cancer cell lines by downregulating the expression of C-X-C motif chemokine receptor 4 (CXCR4)." (PMID 35884547, 2022). "The chemokine receptor CXCR3, another dNK marker, is expressed in TI-NKs of colorectal cancer, breast cancer, melanoma, and glioblastoma, while CXCR4 in NK is upregulated in neuroblastoma and prostate cancer." (PMID 35712510, 2022). "Our data presented here have clearly revealed that Gβγ, PI3Kγ and ARF1 mediate ERK1/2 activation by OR51E2 in prostate cancer cells, which are highly consistent with our previous studies on CXCR4-medited ERK1/2 activation." (PMID 36313302, 2022). "By sponging miRNA-204, lncRNA UCA1 promotes expression level of CXCR4 to enhance metastasis of prostate cancer cells." (PMID 35773731, 2022). "TA-NKs express CD9 and CD49+ in NSCLC, prostate cancer, and melanoma, and CXCR4 is present in TA-NKs of prostate cancer." (PMID 35712510, 2022). "Another factor responsible for bone metastasis of prostate cancer is C-X-C chemokine receptor type 4 (CXCR-4)." (PMID 35773731, 2022). "Further, overexpression of AKT1 in prostate cancers upregulates CXCR4 expression and loss of PTEN in the cells enhances AKT-mediated expression of CXCL12 and CXCR4." (PMID 36012631, 2022). "Resveratrol and its combination with AMD3100 as a CXCR4 inhibitor significantly inhibited dihydrotestosterone (DHT)-induced progression of prostate cancer cell line via affecting the CXCR4 pathway." (PMID 35120520, 2022). "4-fluoro benzoyl-TN-14003(BKT140, motixafortide) is a high-affinity CXCR4 antagonist, which can inhibit the migration of prostate cancer cells." (PMID 35754849, 2022). "We have recently shown that, in addition to Gβγ and PI3Kγ, ARF1 activation also plays an essential role in ERK1/2 activation by CXCR4 in prostate cancer cells." (PMID 36313302, 2022). "A number of GPCRs, including OR51E2 and CXCR4, are over-expressed in prostate cancer patients and regulate prostate cancer cell growth, migration and invasion, and prostate cancer progression." (PMID 36313302, 2022). "Some researchers who analyze the potential role and mechanism of miR-494-3p in regulating CXCR4 posttranscriptionally in human prostate cancer cell lines." (PMID 36003502, 2022). "In prostate cancer, β-adrenoceptor signaling in osteoblasts promotes the secretion of CXCL12 and binding to CXCR4 on surface of prostate cancer cells resulting in increases bone metastasis formation." (PMID 34284799, 2021). "The CXCR4/CXCL12 axis plays essential roles in all stages of prostate cancer progression, including bone metastasis." (PMID 33535458, 2021).
prostate carcinoma (continued). "CXCR4 is a crucial factor involved in bone metastasis of prostate cancer and CXCR4 antagonists inhibit prostate cancer growth and metastasis." (PMID 33493514, 2021). "The CXCL12/CXCR4 axis was shown to be important for the homing of breast and prostate cancer cells to the bone in the early phases of bone metastasis." (PMID 34064589, 2021). "Consistently, loss of PTEN in prostate cancer cells enhances the AKT-mediated expression of CXCL12 and CXCR4." (PMID 34064589, 2021). "For example, C-X-C chemokine receptor type 4 (CXCR4) is a receptor protein that is overexpressed on many cancer cell lines, including the PC-3 prostate cancer cell line." (PMID 33804975, 2021). "Prostate cancer cell lines that overexpress CXCR4 tend to migrate to organs with high levels of C-X-C motif chemokine ligand 12 (CXCL12), such as the bone marrow." (PMID 33804975, 2021). "Hypoxia and the hypoxia-induced expression of the transcription factors HIF-1α or HIF-2α promote bone metastasis of prostate cancer, for example, via upregulation of CXCR4." (PMID 34064589, 2021). "Inhibition of prostate cancer bone metastases was also observed following treatment with neutralizing antibodies to CXCR4 or delivery of a CXCR4 peptide antagonist, TC14012 in vivo." (PMID 33805598, 2021). "Subsequently, the CXCL12/CXCR4 interaction drive the survival and adaptation to the requirements of the bone microenvironment after breast and prostate cancer colonized the bone marrow." (PMID 34064589, 2021). "Our data demonstrate that GA-localized ARF1 inhibitors and ARF1 depletion by siRNA and CRISPR–Cas9 remarkably suppress prostate cancer cell migration and invasion induced by activation of CXCR4, an important GPCR involved in prostate cancer metastasis." (PMID 34022220, 2021). "CXCR4 was upregulated following docetaxel treatment in prostate cancer cell lines including PC-3, C4-2, and MyC-CaP." (PMID 34069563, 2021). "Overexpression of AKT1 in prostate cancer cells was shown to upregulate the CXCR4 expression and, therefore, promotes intraosseous tumor growth as well as the formation of metastases with an osteolytic phenotype." (PMID 34064589, 2021). "In this study, UA was found to downregulate CXCR4 in prostate cancer cells, which correlated with an inhibition of CXCL12-induced migration, reducing metastasis of prostate cancer cells." (PMID 34439409, 2021). "On the other hand, most prostate cancer cells express elevated levels of CXCR4, which makes the CXCL12/CXCR4 axis more active in these cells." (PMID 33535458, 2021). "We also show that depletion of ARF1 by siRNA and CRISPR–Cas9 and inhibition of GA-localized ARF1 activation abolish ERK1/2 activation by CXCR4 and Gβγ translocation to the GA and suppress prostate cancer PC3 cell migration and invasion." (PMID 34022220, 2021). "For instance, the chemokine receptor CXCR4 on breast or prostate cancer cells mediates the chemoattractive effect of osteoblast-derived C-X-C motif chemokine 12 (CXCL12) for the homing of tumor cells to the bone marrow." (PMID 34064589, 2021). "Slug was also found to enhance migration and invasion of prostate cancer cells by activating the CXCR4/CXCL12 axis." (PMID 34118928, 2021). "In this study, a nanostructured lipid carrier (NLC) to encapsulate 1′-acetoxychavicol acetate (ACA) for improved dispersion and targeted delivery to CXCR4-expressing prostate cancer cells was formulated." (PMID 33804975, 2021).
prostate carcinoma (continued). "Previous studies have shown that the CXCL12/CXCR4 chemokine axis plays a critical role in localizing tumor cells to the bone marrow during the early stages of bone metastasis in prostate cancer." (PMID 35177982, 2021). "Although the complete CXCL12/CXCR4-mediated molecular mechanisms through which prostate cancer cells re-establish themselves to the bone are still subject to further investigations, several probable mechanisms have, however, been proposed." (PMID 32585812, 2020). "Blocking the CXCL12/CXCR4 axis via usage of a CXCR4 receptor antagonist (AMD3100) or antibody in prostate cancer cells, however, decreased tumor size and the population of progenitor cells." (PMID 32585812, 2020). "CB2 can be found in connection with C-X-C chemokine receptor type 4 (CXCR4) in breast and prostate cancer cells." (PMID 32316328, 2020). "Expression of CXCL12 and CXCR4 are increased in prostate cancer, with high CXCR4 expression being an indicator for bone metastasis." (PMID 32585812, 2020). "Plerixafor inhibits tumor–stroma interactions through CXCL12/CXCR4 pathway, enhancing efficacy of docetaxel in prostate cancer." (PMID 32824865, 2020). "The specific blockade of the CXCL12/CXCR4 axis in prostate cancer cells using hTERT promoter induced knockdown of CXCR4 decreased bone metastasis." (PMID 32585812, 2020). "Prostate cancer cell lines overexpressing CXCR4 exhibited increased angiogenesis, characterized by enhanced microvascular density and functionality, as well as elevated metastasis to distant organs in a NOD/SCID mice xenograft model." (PMID 32585812, 2020). "In prostate cancer, CXCR4 is overexpressed, and a loss of the tumour suppressor PTEN was reported to activate Akt and regulate the CXCL12/CXCR4 signalling pathway in metastasis." (PMID 32731484, 2020). "The overexpression of CXCR4 or CXCL12γ, an isoform of CXCL12 found in CD44+/CD133+ prostate CSCs, suggests that one mechanism by which the CXCR4/CXCL12 axis promotes metastasis in prostate cancer is the maintenance of stemness in CSCs." (PMID 31991604, 2020). "Prostate cancer cells express high levels of CXCR4, which via a concentration gradient migrate by chemotaxis towards the high CXCL12 expressing bone tissues." (PMID 32585812, 2020). "Inhibition of CXCR4 by plerixafor (AMD3100) or CTE9908 significantly reduced bone metastasis in prostate cancer model mice, as the tumorigenic potential is largely regulated by the CXCR4 signaling pathway in prostate cancer cells." (PMID 32824865, 2020). "In breast and prostate cancer cells, C-X-C chemokine receptor type 4 (CXCR4)-CB2 receptor heteromers regulate proliferation, adhesion, and invasion, thus metastatic potential." (PMID 31979368, 2020). "Using mouse models, it has been shown that breast, lung, and prostate cancer cells overexpressing CXCR4 and CXCR7 increased their ability to extravasate and colonize bone, and CXCR4 inhibition decreased bone and lung metastases." (PMID 30930851, 2019). "SDF-1 treatment also transactivates Her2 via CXCR4 present on cultured human breast and prostate carcinoma cells in a paracrine fashion." (PMID 31331982, 2019). "It has been reported that CB2R can form heteromers with the G protein-coupled chemokine receptor CXCR4 in human breast and prostate cancer cells." (PMID 31024307, 2019). "It has been shown that CXCR4 is upregulated in a number of tumors, such as breast, melanoma, ovarian, and prostate cancer, whereas its expression is low in normal tissues." (PMID 31370904, 2019). "Prostate cancer cells express CXCR4, while bone marrow stromal cells produce CXCL12, and prostate cancer cells migrate to the bone marrow partially via interaction with CXCR4." (PMID 31753020, 2019).